KRAS (KRas proto-oncogene, GTPase)
Diseases named in the same sentence as KRAS in open-access papers (continued):
Sharing a sentence is not in itself a finding about the gene and the disease.
pancreatic ductal adenocarcinoma (continued). "Most reported alterations related to IPMNs and pancreatic ductal adenocarcinomas, including KRAS, GNAS, and BRAF mutations, are absent in ITPNs." (PMID 38539517, 2024). "Furthermore, a study of pancreatic ductal adenocarcinomas (PDAs) derived from intraepithelial neoplasia (panIN) in KRAS mutant cells found that BRG1 assisted in the initiation of panIN and its progression to pancreatic carcinoma." (PMID 36769189, 2023). "The discovery of functionally relevant KRAS effectors in lung and pancreatic ductal adenocarcinoma (LUAD and PDAC) may yield novel molecular targets or mechanisms amenable to inhibition strategies." (PMID 37210549, 2023). "Furthermore, majority of pancreatic ductal adenocarcinoma (PDAC), another common fatal cancer, is initiated by KRAS mutation and hence overexpression of the KRAS protein." (PMID 37051535, 2023). "Hence, to identify the crucial biomarkers involved in the sotorasib resistance, we have retrieved the RNA-seq data from the NCBI GEO database of AMG 510 treated (resistant) and untreated in KRAS G12C-mutant MIA-PaCa2 pancreatic ductal adenocarcinoma cells." (PMID 37396909, 2023). "Furthermore, the enrichment and survival analysis revealed that the small unit ribosomal protein (RP) RPS3 is the crucial biomarker of the AMG 510 resistance in KRAS G12C-mutant MIA-PaCa2 cell pancreatic ductal adenocarcinoma cells." (PMID 37396909, 2023). "Several groups have shown that MYC is a critical effector of mutant KRAS in pancreatic ductal adenocarcinoma (PDAC), prompting us to examine if NUAK1 might be required to support oncogenic proliferation in this context." (PMID 36975767, 2023). "Inhibition of CDK7, a potent transcription regulator, may bring new hope for treating pancreatic ductal adenocarcinoma (PDAC), which is featured by large genetic heterogeneity and abundant KRAS mutations." (PMID 38037549, 2023). "When cells harbor an oncogenic mutation (e.g. KRAS mutation), this normal acinar-to-ductal metaplasia (ADM) response is derailed and initiates a sequence of events that can ultimately lead to pancreatic ductal adenocarcinoma, a highly lethal cancer for which few treatment options exist." (PMID 37387147, 2023). "Additionally, SLC7A11 was also found to be essential for tumor growth by relieving oxidative stress in some oncogenic KRAS-mutant cancers, including pancreatic ductal adenocarcinoma, colorectal adenocarcinoma and LUAD." (PMID 34996469, 2022). "On the contrary, in Kras-driven pancreatic ductal adenocarcinoma (PDAC), HSL is down-regulated as compared to normal pancreas, and the subsequent decrease in HSL-induced lipolysis promotes the metastatic potential of mutated-KRAS PDAC cells." (PMID 35945203, 2022). "KRAS wildtype metastatic pancreatic ductal adenocarcinoma (mPDAC) could represent a distinct molecular entity from other PDACs." (PMID 36209277, 2022). "The context-dependent roles of Fra-1 expression are pinpointed by the inhibitory effects of FOSL1 downregulation on tumor growth, detectable in KRAS-mutated but not in KRAS-wild type PDAC (Pancreatic Ductal AdenoCarcinoma) and LUAD (LUng ADenocarcinoma) cells." (PMID 35326630, 2022). "Notably, the involvement of YAP in KRAS-mediated neoplastic progression in pancreatic ductal adenocarcinoma (PDAC), underscores the potential crosstalk between YAP/TAZ and RAS signaling pathways in PDAC." (PMID 35439973, 2022). "KRAS is a critical driver of pancreatic ductal adenocarcinoma (PDAC) initiation and maintenance." (PMID 34998392, 2022).
pancreatic ductal adenocarcinoma (continued). "The utility of circulating tumour DNA (ctDNA) for longitudinal tumour monitoring in pancreatic ductal adenocarcinoma (PDAC) has not been explored beyond mutations in the KRAS proto-oncogene." (PMID 35392854, 2022). "Intriguingly, extensive in vitro and in vivo studies performed by the authors revealed that KRAS-driven pancreatic ductal adenocarcinomas display a dependency on glycolysis and the need to buffer intracellular pH through the bicarbonate producing activity of CA IX." (PMID 34948200, 2021). "Ductal pancreatic adenocarcinoma KRAS mutant revealed early metastasis to the liver." (PMID 35154607, 2021). "Similarly, the lysosomes of pancreatic ductal adenocarcinoma (PDAC) cells with mutant KRAS show a >0.5 pH unit decrease compared to normal human pancreatic duct epithelial cells or PDAC cells lacking oncogenic KRAS." (PMID 34055797, 2021). "Therefore, the pancreatic ductal adenocarcinoma with wild-type KRAS seems to have the most favorable prognosis when accomplished by gHRR mutations, which is probably responsible for the best response to therapy." (PMID 33800556, 2021). "Akt1 activity in combination with KRAS oncogenic mutant could accelerate pancreatic progression toward invasive pancreatic ductal adenocarcinoma." (PMID 35154607, 2021). "Also, concomitant mutations of KRAS and LRP1B were associated with worse disease-free survival in pancreatic ductal adenocarcinoma." (PMID 34680332, 2021). "In addition, hnRNPA2B1 can interact with phosphorylated KRAS protein, functioning as a regulator of KRAS-dependent tumorigenesis through the critical pancreatic ductal adenocarcinoma signaling pathway PI3K/AKT." (PMID 34044823, 2021). "A previous study showed that pancreatic ductal adenocarcinoma (PDACs) cells that express an activated KRAS increase the expression of CA9, via stabilization of hypoxia-inducible factor 1 subunit alpha (HIF1A) and HIF2A, which eventually regulates the pH and glycolysis." (PMID 33456371, 2020). "Three studies recently published simultaneously illustrated synergistic activity of concomitant inhibition of autophagy and MAPK pathway in patient-derived xenografts of KRAS mutant pancreatic ductal adenocarcinoma, NRAS mutant melanoma and B-RAF mutant colorectal tumor." (PMID 32560574, 2020). "However, these metabolic circuits are dispensable in KRAS-driven pancreatic ductal adenocarcinoma (PDAC) cells." (PMID 31681559, 2019). "We acknowledge that sharing the same KRAS mutation alone does not guarantee genetic relatedness, but the G12R mutation is relatively uncommon (only ~10–15% of pancreatic ductal adenocarcinomas)." (PMID 30467323, 2019). "Oncogenic KRAS is the key driver of pancreatic ductal adenocarcinoma (PDAC)." (PMID 30470748, 2018). "Deltarasin was the first small molecule effectively targeting the spatial organization of Ras by competing for the farnesyl-binding pocket of PDEδ and thereby resulting in a reduced proliferation of oncogenic KRas-dependent pancreatic ductal adenocarcinoma cells." (PMID 27094677, 2016). "Recently, we have reported that the small-molecule Deltarasin binds to the prenyl-binding pocket of PDEδ, and impairs Ras enrichment at the plasma membrane, thereby affecting the proliferation of KRas-dependent human pancreatic ductal adenocarcinoma cell lines." (PMID 27094677, 2016).
pancreatic ductal adenocarcinoma (continued). "Focusing on KRAS G12D, GFH375 (VS-7375) has received fast track designation (FTD) for first-line treatment of patients with KRAS G12D mutation-positive locally advanced or metastatic pancreatic ductal adenocarcinoma, but is currently in phase I/II clinical study (NCT06500676)." (PMID 41361128, 2025). "Importantly, roughly 90% of patients with pancreatic ductal adenocarcinomas have a KRAS mutation but, for those patients without a KRAS mutation, an NRG1 fusion can sometimes be found." (PMID 38369520, 2024). "Oncogenic KRAS mutations are absent in approximately 10% of patients with metastatic pancreatic ductal adenocarcinoma (mPDAC) and may represent a subgroup of mPDAC with therapeutic options beyond standard-of-care cytotoxic chemotherapy." (PMID 36209277, 2022). "Similarly, mutant KRAS-G12V is sufficient to induce pancreatic ductal adenocarcinoma in mice, when expressed in embryonic cells of acinar lineage, whereas chronic inflammation in combination with KRAS-G12V expression is required for pancreatic tumorigenesis in adult mice." (PMID 34302118, 2021). "RAGE and its ligands also play vital roles in pancreatic ductal adenocarcinoma (PDAC) by increasing NF-κB activity and may be directly activated RAS which KRAS oncogenic mutations are observed in up to 30% of all cancers and in PDAC KRAS mutation is in nearly all tumors." (PMID 34199060, 2021). "Furthermore, the preclinical efficacy of the trametinib (MEK1/2i) + hydroxychloroquine combination against KRAS-driven pancreatic ductal adenocarcinoma or NRAS-driven melanoma has already led to multiple clinical trials (NCT03825289, NCT04145297, and NCT03979651) in these areas." (PMID 34298710, 2021). "In contrast to IPMNs which show KRAS-Mutations in approximately 60% of cases and ductal adenocarcinoma of the pancreas which shows KRAS mutations in almost all cases, no KRAS mutations were observed in a series of 24 ITPNs with invasive (n = 13) or non-invasive tumor growth (n = 11)." (PMID 30753991, 2019). "Furthermore, Chen NM and colleagues found that KRAS signaling was required for EZH2-mediated transcriptional activation of the inflammatory transcription factor nuclear factor of activated T cells 1 (NFATC1) in pancreatic ductal adenocarcinoma cells." (PMID 29335012, 2018). "Interestingly, activated β-catenin signaling has been observed to antagonize KRAS-induced transformation; but the inflammatory state provides a break for constitutively-active KRAS to induce early events in pancreatic ductal adenocarcinoma initiation by blocking acinar regeneration." (PMID 28383487, 2017). "This evidence-mapping review evaluates current quantitative reporting approaches in pancreatic ductal adenocarcinoma (PDAC) and examines the potential role of KRAS mutant ctDNA as a biologically grounded reference metric." (PMID 42073641, 2026). "In pancreatic ductal adenocarcinoma (PDAC), KRAS further increases the metabolic demands of tumor cells by enhancing glycolytic pathways, which exacerbates local lactate accumulation and contributes to immune suppression." (PMID 40303413, 2025). "The involvement of cell death pathways in the early stage of pancreatic ductal adenocarcinoma (PDAC) development, especially KRAS-dependent acinar-to-ductal metaplasia (ADM), remains to be investigated." (PMID 39971907, 2025).
pancreatic ductal adenocarcinoma (continued). "For instance, in pancreatic ductal adenocarcinoma (PDAC), mutant KRAS signaling promotes mitochondrial fragmentation via enhanced Drp1 activity, which is essential for KRAS-driven tumor growth." (PMID 40724998, 2025). "Using a conceptual framework of pancreatic ductal adenocarcinoma, we show that cancer cells that survive CRISPR-mediated ablation of mutant KRAS are dependent on STAT3 function to maintain tumorigenicity." (PMID 40859018, 2025). "Pancreatic ductal adenocarcinoma (PDA) is one of the most lethal types of cancer, and KRAS oncogene occurs in over 90% of cases." (PMID 38797819, 2024). "To do so, we utilized an isogenic pancreatic ductal adenocarcinoma cell line (PATU-8902 FKBP12F36V-KRASG12V; KRAS–/–) that we previously developed to study KRASG12V degradation in vitro." (PMID 39718828, 2024). "Therapies targeting pancreatic ductal adenocarcinoma (PDAC), driven in most cases by the KRAS oncogene, continue to present a clinical challenge." (PMID 38413839, 2024). "For example, in pancreatic ductal adenocarcinoma (PDAC), tumor cells that survived Kirsten rat sarcoma viral oncogene homolog (KRAS) oncogene ablation were reliant on oxphos and had features similar to cancer stem cells." (PMID 37779896, 2023). "Oncogenic KRAS activates GOT1/2 to promote glutamine metabolism, which supports aspartate production in pancreatic ductal adenocarcinoma (PDAC) cells." (PMID 37488138, 2023). "Previously, inhibition of the ATR-CHK1 DDR pathway in expressed pancreatic ductal adenocarcinoma (PDAC) cells resulted in ERK activation, which is a key downstream protein of KRAS." (PMID 35563313, 2022). "Remarkably, mutant KRAS suppression leads to an increased autophagic flux rather than decreased basal levels, and the chronic ablation of KRASG12D results, in mouse pancreatic ductal carcinoma cells, in more dependence on autophagy." (PMID 35883626, 2022). "In pancreatic ductal adenocarcinoma (PDAC), another KRAS‐driven cancer, SOX9 is a critical mediator of KRAS‐induced PDAC initiation of pancreatic acinar cells in mouse model." (PMID 34919787, 2022). "Pancreatic ductal adenocarcinomas (PDAC) and poorly differentiated pancreatic neuroendocrine (NE) carcinomas are KRAS mutant malignancies with a potential common cell of origin." (PMID 34657147, 2022). "Pancreatic ductal adenocarcinoma (PDAC), one of the most aggressive types of cancer, is characterized by aberrant activity of oncogenic KRAS." (PMID 35286386, 2022). "Ciliogenesis and Hedgehog signaling are suppressed downstream of KRAS all through acinar-ductal metaplasia in mice, which might be employed as a method to limit the progression of early lesions and, therefore, the advancement to pancreatic ductal adenocarcinoma." (PMID 36046242, 2022). "In this review, we will present an updated summary of mutant KRAS role in the initiation, progression, and modulation of the TME of pancreatic ductal adenocarcinoma (PDAC)." (PMID 34638560, 2021). "In pancreatic ductal adenocarcinoma (PDAC), lncRNA UCA1 regulated miR-590-3p to increase the expression of oncogenic Kirsten rat sarcoma viral oncogene homolog (KRAS) protein, and KRAS itself can promote lncRNA UCA1 expression." (PMID 33936199, 2021). "Overexpression of the mutant form of the proto-oncogene GTPase KRAS (KRASG12V) in pancreatic ductal adenocarcinoma (PDAC) samples increases, whereas knockdown of KRAS decreases, BCAT2 protein, with a minimal effect on BCAT2 mRNA level." (PMID 34354601, 2021).
pancreatic ductal adenocarcinoma (continued). "A similar observation has also been reported for pancreatic ductal adenocarcinoma, where exogenous addition of human recombinant TIMP‐1 significantly increased proliferation of pancreatic ductal cells, but only in KRAS‐transformed cells." (PMID 31545548, 2019). "MiR-206 has been reported as a tumor suppressor gene in human pancreatic ductal adenocarcinoma (PDAC), directly targeting oncogenes KRAS and annexin a2 (ANXA2)." (PMID 27191262, 2016). "In pancreatic ductal adenocarcinoma, AMPA receptor signaling to KRAS and MAPK promoted migration and invasion." (PMID 25326682, 2014). "In pancreatic ductal adenocarcinoma (PDAC), activated kirsten rat sarcoma viral oncogene homolog (KRAS) upregulates iron‐sulfur clusters 2 expression and promotes α‐KG catabolism in mice, which leads to suppression of TET3 and DNA 5mC‐dependent PDAC cell proliferation." (PMID 40599235, 2025). "In pancreatic ductal adenocarcinoma (PDAC), disruption of the KRAS-HSL axis resulted in decreased lipid storage, tumor cell metabolic reprogramming, and reduced invasive and metastatic ability, indicating that the KRAS-HSL axis is a potential therapeutic target for PDAC." (PMID 39125923, 2024). "Pancreatic ductal adenocarcinoma (PDAC) has been reported to be an NRG1 fusion-enriched tumor; the overall incidence of NRG1 + PDAC is estimated to be 0.48%, and the incidence of NRG1 + PDAC seems to be enriched in KRAS-wild-type PDAC." (PMID 38173003, 2024). "Pancreatic ductal adenocarcinoma is characterized by the lack of druggable drivers, e.g. KRAS, although emerging studies are showing promising results by more selective KRAS inhibitors." (PMID 38650175, 2024). "The results demonstrated that while p16 inactivation alone did not initiate tumorigenesis, combined with KRAS activation, it significantly accelerated tumor progression and metastasis, closely resembling human pancreatic ductal adenocarcinoma." (PMID 38666907, 2024). "Interestingly, we also showed that silencing of miR-92a-3p also increases BIM protein expression and sensitivity to cisplatin in another KRAS-driven tumor cell line model distinct from LUAD, the pancreatic ductal adenocarcinoma." (PMID 37704611, 2023). "Previously, hnRNPA2B1 was reported to interact directly with KRAS proteins as a partner without regulating KRAS expression in pancreatic ductal adenocarcinoma (PDAC)." (PMID 37716979, 2023). "After in vivo transplantation, PDLOs with oncogenic KRAS form heterogeneous dysplastic lesions, PDLOs carrying oncogenic KRAS with CDKN2A knockout give rise to pancreatic ductal adenocarcinomas, and PDLOs carrying oncogenic GNAS form intraductal papillary mucinous neoplasia-like structures." (PMID 37146581, 2023). "For instance, in a clinical study that evaluated the presence of mutant KRAS in plasma-derived EV DNA of early-stage pancreatic ductal adenocarcinoma (PDAC) patients, 66% of the patients (22/33 patients) were positive for mutant KRAS whereas only 7.4% of age-matched control samples were positive." (PMID 37397375, 2023). "These pan-KRAS drugs would be suited for non-KRAS G12C tumors such as those predominant in pancreatic ductal adenocarcinoma (PDAC)." (PMID 38023987, 2023). "For instance, hnRNPA1 could recognize the specific DNA conformation of KRAS, a G4 structure, and form an EGF-KRAS-ILK-hnRNPA1 regulatory loop to maintain the invasive activity of pancreatic ductal adenocarcinoma (PDAC) cells." (PMID 35879279, 2022).